ASPM (assembly factor for spindle microtubules)
Diseases named in the same sentence as ASPM in open-access papers (continued):
Sharing a sentence is not in itself a finding about the gene and the disease.
colorectal cancer (2 papers, 2020 to 2025). A primary or metastatic malignant neoplasm that affects the colon or rectum. "Because of high ASPM levels have been linked with tumor development and progression in colorectal cancer as well." (PMID 40873651, 2025).
communication disorder (2 papers, 2020 to 2022). A disorder characterized by an individual's inability to comprehend or share ideas or feelings because of an impairment in language, speech, or hearing. "Thus, future research might investigate whether ASPM is a candidate gene for communication disorders and whether it is a genetic marker specific to individuals who speak a tone language (but not individuals who speak a nontone language)." (PMID 32537487, 2020). "Future studies might examine the ASPM gene as a potential genetic marker for prosodic differences in ASD, shedding light onto the etiologies of communications disorders that contribute to distinct cross-linguistic patterns of intonation in ASD." (PMID 35675372, 2022).
endometrial carcinoma (2 papers, 2020 to 2022). A malignant tumor arising from the epithelium that lines the cavity of the uterine body. "In this study, our results first showed that high levels of ASPM were related to endometrial cancer." (PMID 32555395, 2020). "Aberrant expression levels of four genes out of 12 core DEGs showed a significant (P < 0.05)association with poor prognosis of endometrial cancer, and this included two up-regulated (TOP2A and ASPM) and two down-regulated (FOXL2 and EFEMP1) genes." (PMID 32555395, 2020). "When combined with the function of the gene, ASPM is expected to become a new molecule for detection and treatment of this disease although its mechanism in endometrial cancer is yet to be studied." (PMID 32555395, 2020). "Analysis of qRT-PCR assay revealed that expression of mRNA for TOP2A and ASPM are up-regulated in endometrial cancer cells, whereas those of EFEMP1 and FOXL2 are down-regulated." (PMID 32555395, 2020). "We found up-regulation of TOP2A and ASPM in endometrial cancer tissues or cells, while EFEMP1 and FOXL2 were down-regulated." (PMID 32555395, 2020). "Furthermore, a cross comparison of common DEGs across the three datasets revealed that TOP2A, ASPM, FOXL2 and EFEMP1 were potential biomarkers for distinguishing endometrial cancer, and this was significantly associated with the survival ratios among patients." (PMID 32555395, 2020). "Further validation in endometrial cancer cells showed that indeed TOP2A, ASPM, FOXL2 and EFEMP1 were significantly regulated." (PMID 32555395, 2020). "Particularly, expression of TFAP2A, MMP12, TOP2A, ASPM and CFB were higher in endometrial cancer relative to normal tissues." (PMID 32555395, 2020). "In summary, four core genes (TOP2A, ASPM, EFEMP1 and FOXL2) and several interesting pathways involved in endometrial cancer were identified." (PMID 32555395, 2020). "Finally, we performed a survival analysis and identified four genes (TOP2A, ASPM, EFEMP1, and FOXL2) that play key roles in endometrial cancer." (PMID 32555395, 2020). "Currently, there are no studies on the role of ASPM and FOXL2 in endometrial cancer." (PMID 32555395, 2020).
epilepsy (2 papers, 2022 to 2023). A brain disorder characterized by episodes of abnormally increased neuronal discharge resulting in transient episodes of sensory or motor neurological dysfunction, or psychic dysfunction. "Finally, although this question remains unaddressed, the loss of normal excitatory–inhibitory neuronal balance in the cerebral cortex of patients carrying ASPM mutations may also explain the high rate of epilepsy in patients without MCD." (PMID 37443841, 2023).
medulloblastoma (2 papers, 2023 to 2024). A malignant, invasive embryonal neoplasm arising from the cerebellum. "In medulloblastoma, ASPM is overexpressed and its knockdown inhibits both tumor and stem cell proliferation." (PMID 39594769, 2024). "While the growth inhibition in cerebellar and medulloblastoma has been confirmed in ASPM knockout animal models, an increase of DNA damage and apoptosis was also noted." (PMID 37599996, 2023).
melanoma (2 papers, 2010 to 2020). A malignant, usually aggressive tumor composed of atypical, neoplastic melanocytes. "In metastatic melanoma tissues, ASPM gene is highly expressed, and ASPM overexpression improves the invasion ability of melanoma cells, indicating that ASPM may mediate the invasion and metastasis of tumours." (PMID 32667745, 2020). "Here we uncovered a pro-invasive role for ASPM in melanoma cells." (PMID 20520718, 2010). "Functional assays on a subset of these candidates, including MET, ASPM, AKAP9, IMP3, PRKCA, RPA3, and SCAP2, validated their pro-invasion activities in human melanoma cells." (PMID 20520718, 2010). "Correspondingly, we also demonstrated that overexpression of ASPM in WM3211, a weakly invasive human melanoma cell line, consistently increased invasion through matrix in the Boyden Chamber assay (p<0.05)." (PMID 20520718, 2010). "To this end, we selected 6 genes from the candidate list (ASPM, AKAP9, IMP3, PRKCA, RPA3, and SKAP2) based on literature support (see Discussion) to determine whether their knockdown would impact on the invasion of a human melanoma cell, 1205LU." (PMID 20520718, 2010).
metastatic prostate carcinoma (2 papers, 2021 to 2024). A carcinoma that arises from the prostate gland and has spread to other anatomic sites. "For example, ASPM expression is incrementally up-regulated in primary and metastatic prostate cancer." (PMID 33937050, 2021).
schizophrenia (2 papers, 2017 to 2020). A major psychotic disorder characterized by abnormalities in the perception or expression of reality. "In accordance with this, DISC1, ANK3 and ASPM, whose mutations are associated with schizophrenia, bipolar disorder and autism spectrum disorder, have been shown to regulate Wnt/β-catenin signaling activity during cortical neurogenesis." (PMID 28103279, 2017).
ZIKV infection (2 papers, 2021 to 2022). "Dysregulation of the neuronal genes, such as RBBP8, ASPM, AXL, TBR2, MCPH1, and CENPF upon ZIKV infection may cause different neurological or brain development related disorders." (PMID 33891593, 2021).
acute myeloid leukaemia (1 paper, 2020). "We also noted that ASPM may have a tumour suppressive effect in acute myeloid leukaemia (LAML), in which ASPM expression is lower in cancer tissues than in adjacent, normal tissues." (PMID 31905171, 2020).
Alstrom syndrome (1 paper, 2019). A multisystemic disorder characterized by cone-rod dystrophy, hearing loss, obesity, insulin resistance and hyperinsulinemia, type 2 diabetes mellitus, dilated cardiomyopathy (DCM), and progressive hepatic and renal dysfunction. "ALMS1 (Alstrom syndrome gene), ASPM (abnormal spindle-like microcephaly-associated protein), and PDE4DIP (phosphodiesterase 4D interacting protein) bind to microtubules and play a role in the formation of microtubule-based structures, including the centrosome and mitotic spindle." (PMID 31827074, 2019).
Anaplastic Thyroid Carcinomas (1 paper, 2022). "Abnormal spindle-like microcephaly-associated protein (ASPM) is closely correlated with several malignant tumors, whereas little is known about the role of ASPM in anaplastic thyroid cancer (ATC)." (PMID 35387319, 2022).
Angelman syndrome (1 paper, 2011). A neurogenetic disorder characterized by severe intellectual deficit and distinct facial dysmorphic features. "Given this scenario, we screened a human fetal brain library with an ASPM C-terminus bait and identified Angelman syndrome (AS) gene product UBE3A as an interacting partner." (PMID 21633703, 2011). "The analysis identified Angelman syndrome gene product UBE3A as an ASPM interactor." (PMID 21633703, 2011).
benign cystadenoma (1 paper, 2011). "The lysate from a benign cystadenoma case (control, sample 1153-A1) had one of the lowest levels of ASPM protein in comparison to the other primary cell culture lysates." (PMID 21505456, 2011).
brain malformations (1 paper, 2025).
colitis (1 paper, 2024). Inflammation of the colon. "A PPI network based on DEGs was constructed using STRING, and a highly interconnected cluster was identified as a potential functional molecular complex of colitis, including 8 hub genes, that is, NDC80, PBK, CEP55, RRM2, ASPM, NCAPG, TOP2A, and CDKN." (PMID 38661103, 2024).
COVID-19 (1 paper, 2023). A disease caused by infection with severe acute respiratory syndrome coronavirus 2. "We screened for statistically significant hub genes and found that ACTB was in low expression of both BD and COVID-19, and ASPM, CCNA2, CCNB1, and CENPE were in low expression of BD and high expression of COVID-19." (PMID 37335738, 2023).
diabetes (1 paper, 2022). "Nonetheless, none of the expression of ASPM, CDC20, DLGAP5, BUB1B, CDCA8, and NCAPG was related to BMI and diabetes." (PMID 36186000, 2022).
endometrioid adenocarcinoma (1 paper, 2020). An adenocarcinoma characterized by the presence of malignant glandular epithelial cells resembling endometrial cells. "In addition, MAL and ASPM had higher expression levels in EC tissues of different subtypes, such as serous carcinoma, endometrioid adenocarcinoma and mixed serous and endometrioid adenocarcinoma." (PMID 32099532, 2020).
ependymoma (1 paper, 2010). A WHO grade II, slow growing tumor of children and young adults, usually located intraventricularly. "ASPM immunohistochemical expression in ependymomas at diagnosis and relapse." (PMID 20885975, 2010). "To confirm the changes in expression of MT3 and ASPM in an independent cohort, we studied the expression of these two genes on a TMA of childhood ependymomas composed of 24 tumours at diagnosis with at least one relapse." (PMID 20885975, 2010).
Hearing impairment (1 paper, 2020). A decreased magnitude of the sensory perception of sound. "One notable additional feature was bilateral hearing impairment (HI), observed in two (out of three) patients of family 14 who carry a protein‐truncating ASPM mutation." (PMID 32677750, 2020).
infiltrating ductal carcinoma (1 paper, 2022). "ASPM expression showed the most significant increase in infiltrating ductal carcinoma and infiltrating lobular carcinoma." (PMID 35515103, 2022).
liver fibrosis (1 paper, 2022). "With the progression of liver fibrosis and the closer tumor center of HCC, the higher expression of ASPM was identified." (PMID 36304312, 2022). "More significantly, the results showed that there were some genes such as ASPM, NUSAP1, and PBK showed increased expression levels in non-tumor tissues with advanced liver fibrosis." (PMID 36304312, 2022).
lymph node metastasis (1 paper, 2021). "Patients with a high expression of ASPM (HGNC:19048) were at more advanced clinical stages and were more prone to lymph node metastasis." (PMID 35087827, 2021).
malaria (1 paper, 2012). Malaria is a serious and sometimes fatal disease caused by a parasite that commonly infects a certain type of mosquito which feeds on humans. "HDIs contain several candidate genes for local adaptation identified in previous studies, such as TRPV6, ASPM, prodynorphin [PDYN;], the duffy blood group locus involved in malaria resistance [DARC;], or the ectodysplasin A receptor [EDAR;]." (PMID 22439654, 2012).
neuroblastoma (1 paper, 2022). Neuroblastoma (NB) is the most common solid, extracranial childhood tumor. "Expression of bub1 was found to significantly affect overall survival and event-free survival of patients with neuroblastoma, positively correlate with the expressions of tpx2 and the ASPM gene, and negatively correlate with host immune infiltration." (PMID 36237324, 2022).
osteosarcoma (1 paper, 2023). A usually aggressive malignant bone-forming mesenchymal neoplasm, predominantly affecting adolescents and young adults. "Eight out of the 54 hub‐genes (ASPM, CENPF, KIF14, KIF20A, RCC1, SMC2, SRC, and TOP2A) were significantly decreased after NACT (criteria: |fold change| ≥ 2 and adjusted p value < 0.05), consistent with the central role of these hub genes in osteosarcoma." (PMID 37457661, 2023).
papillary renal cell carcinoma (1 paper, 2022). A rare subtype of renal cell carcinoma, arising from the renal tubular epithelium and showing a papillary growth pattern, which typically manifests with hematuria, flank pain, palpable abdominal mass or nonspecific symptoms, such as fatigue, weight loss or fever. "Interestingly, these KNL1-related molecules (e.g., BUB1, ASPM, TOP2A) have been implicated in immune infiltration in papillary renal cell carcinoma in another report." (PMID 36685823, 2022).
tumor (81 papers, 2008 to 2025). "Bioinformatics methods revealed high expression of ASPM in tumor tissues and its association with low patient survival." (PMID 40979592, 2025). "In this study, we screened the ASPM gene via raw letter analysis and found that ASPM was highly expressed in tumor tissues and was closely associated with the survival of NSCLC patients." (PMID 40979592, 2025). "ASPM is significantly upregulated in NSCLC tumor tissues and is strongly associated with reduced patient survival." (PMID 40979592, 2025). "In the TCGA cohort, high ASPM mRNA expression was significantly associated with larger tumor size, higher tumor grade, high mitotic score, LVI, ER positivity, and HER2 negativity (p < 0.001)." (PMID 39594769, 2024). "High cytoplasmic expression of ASPM protein was significantly associated with higher tumor grade, elevated mitotic scores, increased Ki67 labeling index, pronounced nuclear pleomorphism, and poor Nottingham Prognostic Index (NPI) (p < 0.001);." (PMID 39594769, 2024). "We revealed a significant association between high ASPM mRNA and protein expression, with poor clinicopathological parameters including high tumor grade, high mitotic score, and NPI." (PMID 39594769, 2024). "Overexpression of CCNB1, CCNB2, DLGAP5, and ASPM is associated with tumor progression and poor prognosis." (PMID 39045407, 2024). "The results of this report reveal the important role of ASPM in cancer and provide an underlying mechanism and potential relationship between ASPM and tumor immunity." (PMID 35515103, 2022). "Increasing studies have shown that ASPM is overexpressed in multiple tumor tissues and is associated with disease progression." (PMID 35387319, 2022). "The underlying mechanism between ASPM expression and tumor-infiltrating immune cells should be further explored." (PMID 35515103, 2022). "The study also identified other genes with significant association within at least one tumor type or breed, including ASPM, which functions in the mitotic spindle, and SPEF2 and FSIP2, both related to spermatogenesis." (PMID 34344882, 2021). "CCNB2 expression was associated with tumor stage (P = 0.01), and ASPM expression was associated with new tumor events (P = 0.03)." (PMID 32685486, 2020). "This suggests that the role of ASPM in regulating the underlying mechanisms of tumorigenesis and progression is identical in different tumours." (PMID 32047816, 2020). "ASPM (abnormal spindle-like microcephaly associated) is an oncogene that promotes tumor aggression in PDAC, and overexpression is associated with poor prognosis." (PMID 31379917, 2019). "Overexpression of ASPM correlated with the presence of tumor metastasis, and was significantly associated with a worse prognosis." (PMID 31106147, 2019). "Here too, increased ASPM levels cause tumor growth and are seen in medulloblastomas while its reduction causes a decrease in tumor proliferation." (PMID 29352115, 2018). "For ASPM, an association between cytoplasmic staining levels and tumour invasiveness was identified." (PMID 24830737, 2014). "One tumor-associated embryonic gene, ASPM, regulates symmetric versus asymmetric cell divisions in progenitor cells and also regulates WNT signaling in the developing brain." (PMID 23506684, 2013). "Statistical analysis for the 18 primary culture samples with associated clinical data indicated that strong cytoplasmic ASPM staining levels were significantly associated with a low tumour grade (P=0.0351)." (PMID 21505456, 2011). "Further ASPM has been implicated in tumor cell proliferation and growth MAP2 stabilizes and interacts with microtubules during the growth, differentiation, and development of neurons." (PMID 18541031, 2008).